PRL (prolactin)
Diseases named in the same sentence as PRL in open-access papers (continued):
Sharing a sentence is not in itself a finding about the gene and the disease.
hyperprolactinemia (continued). "PRLRs in pancreatic β cells improve insulin release in response to blood glucose at physiological PRL level, though hyperprolactinaemia can induce hyperglycaemia and IR." (PMID 39663784, 2024). "In the context of hyperprolactinemia, the female body has unique characteristics, as the menstrual cycle, menopause, and pregnancy influence prolactin secretion." (PMID 38578473, 2024). "While others have more commonly reported hyperprolactinemia likely due to stalk disruption, in our patient, low levels of prolactin levels were seen suggesting lactotroph dysfunction." (PMID 38290212, 2024). "The prolactin levels in patients with drug-induced hyperprolactinemia (n = 160) ranged from 37 to 720 ng/mL (mean, 86.97 ± 112.90 ng/mL; median, 85 ng/mL)." (PMID 39420933, 2024). "While the mechanism and nature of the relationship are not well understood, individuals with hyperprolactinemia report a graded reduction in sexual desire as well as other sexual dysfunction when compared to individuals with normal prolactin levels." (PMID 39273752, 2024). "The aim of this article was to present the current knowledge about possible relationships between prolactin/hyperprolactinaemia and endometriosis-related infertility." (PMID 39407928, 2024). "Individuals with known pituitary diseases, hyperprolactinemia and medications known to alter circulating PRL levels were excluded by all primary studies." (PMID 38760578, 2024). "Individuals with pregnancy, lactation and hyperprolactinemia, drugs known to alter circulating PRL levels, or pituitary diseases had been excluded." (PMID 38760578, 2024). "Some controversy still remains regarding the relevance of the magnitude of prolactin level elevation in predicting the etiology of hyperprolactinemia." (PMID 39420933, 2024). "Endocrine Society guidelines state that a single measurement of serum PRL concentrations permits the diagnosis of hyperprolactinemia." (PMID 38370355, 2024). "High IGF1 and GH (nadir in OGTT—oral glucose tolerance test) levels at diagnosis were detected in 11 cases, with a mean value of 3.47 ± 1.56 (×ULN—upper normal limit), where 3 cases had hyperprolactinemia and 2 cases presented with mixed PRL- and GH-secretion." (PMID 38248047, 2024). "Three of the meta-analyses discussed the efficacy of adjunctive aripiprazole and came to a positive conclusion that aripiprazole can effectively reduce the serum prolactin level in patients with antipsychotic-induced hyperprolactinemia." (PMID 38505795, 2024). "Other sex hormones, such as PRL and E2, besides hyperprolactinemia leading to decreased libido and sexual dysfunction through hypothalamic–pituitary–gonadal axis regulation, have not been clearly implicated in directly causing ED." (PMID 39346801, 2024). "Although elevated levels of PRL (hyperprolactinemia) can have adverse effects, such as decreased libido, amenorrhea, infertility, and breast-related issues, discrete increases in serum PRL display beneficial effects with reduced side effects." (PMID 39499702, 2024). "Clinical studies in patients with hyperprolactinemia demonstrated that headache is decreased, in some cases diminished via downregulation of PRL." (PMID 36967387, 2023). "Mild hyperprolactinaemia is a condition in which PRL is slightly increased and occurs for a variety of reasons, including also normal physiological response to stress in patients without a prolactinoma." (PMID 38075075, 2023). "Incidences of headache were similar across subgroups, while the incidence of increased blood prolactin/hyperprolactinemia was slightly higher (19.0%) in the PP6M/PP6M subgroup compared with the PP3M/PP6M subgroup (15.8%)." (PMID 37480362, 2023). "In relation to hormonal hypersecretion, the patient with uncontrolled hypercortisolism normalized his urinary cortisol, and 2 out of 7 patients with uncontrolled hyperprolactinemia normalized their prolactin levels." (PMID 37720528, 2023).
hyperprolactinemia (continued). "Hyperprolactinemia on day 28 was present in 53.8% of patients in which prolactin levels were <20 ng/ml on day 0 and in 46.2% of patients in which prolactin levels were >/=20 ng/ml on day '0'." (PMID 38249246, 2023). "These tumors resemble a mammosomatotroph tumor, secreting GH and PRL, but also express variable GATA and βTSH, producing overt acromegaly associated with hyperprolactinemia." (PMID 37762304, 2023). "Taking this into account, most studies have established different PRL values for male and female subjects for defining hyperprolactinemia." (PMID 36305138, 2023). "Dealing with the endocrinological outcome, all patients with hyperprolactinemia normalized the PRL value; nine (34.6%) patients were suffering from hypopituitarism." (PMID 37685541, 2023). "Nevertheless, a serum PRL value higher than 25 ng/mL is considered as hyperprolactinemia; it is recommended that borderline cases (20–40 ng/mL) are verified twice before reporting to avoid over diagnosis." (PMID 36596817, 2023). "AMH level was lower (3.57 ± 1.7 vs. 3.22 ± 3.14 ng/ml; p = 0.025), and prolactin level was slightly higher (14.17 ± 4.92 vs. 21.69 ± 14.3, p = 0.007) in patients with hyperprolactinaemia, both within the normal range." (PMID 36477597, 2023). "This research team recommends monitoring menses and prolactin levels and preventing hyperprolactinemia in order to avoid short- or long-term consequences." (PMID 37759839, 2023). "Because the study population included a heterogenous group of women with prolactin excess, it cannot be totally excluded that cardiometabolic effects of both treatment options depend on the reason for hyperprolactinemia." (PMID 37176648, 2023). "A comparison of VAC and bromocriptine use on PRL levels in women with mild hyperprolactinaemia found a comparable reduction in both groups." (PMID 38075075, 2023). "As she suffered from hormone-dependent breast cancer and presented paliperidone-induced hyperprolactinemia, we switched this drug to aripiprazole, a prolactin-sparing antipsychotic." (PMID 38283524, 2023). "Neurological disorders such as seizures were more prevalent among active SLE cases with hyperprolactinemia than those with normal prolactin levels in the present study (P value = 0.007)." (PMID 37864188, 2023). "Of these 31 hyperprolactinemia patients, two (6.5%) had presented with normalized PRL during testing." (PMID 36596817, 2023). "Antipsychotics that block dopamine-D2 receptors, which consequently inhibit the action of dopamine on prolactin secretion resulting in hyperprolactinemia." (PMID 37608079, 2023). "Anti-prolactin autoantibodies were also identified in SLE patients, considering that all SLE patients with anti-PRL autoantibodies had hyperprolactinemia (hPRL) and only 31.7% of SLE patients classified with idiopathic hPRL had anti-prolactin antibodies." (PMID 37299501, 2023). "Serum prolactin level should be screened in obese patients, especially those with long-term and severe obesity, in order to avoid miss-diagnosis of hyperprolactinemia." (PMID 38093965, 2023). "Another option to study the link between PRL and headache is by investigating hyperprolactinemia, a condition characterised by elevated serum PRL levels of more than 0.1–0.2 mg/l." (PMID 36967387, 2023). "Diagnosing hyperprolactinemia relies on measuring prolactin levels in the blood, and elevated serum levels of prolactin are typically indicative of prolactinoma." (PMID 37905282, 2023). "Hyperprolactinemia was present in 71.3% of the sample, and sexual dysfunction was significantly higher in these women than in those with prolactin levels within the normal range." (PMID 37759839, 2023). "PRL-increasing-Aps: antipsychotics related with hyperprolactinemia or elevated prolactin levels including fluphenazine, risperidone, haloperidol, amisulpride, sulpiride, and paliperidone." (PMID 37344770, 2023).
hyperprolactinemia (continued). "Macro-PRL has been found in 10–25% of patients with hyperprolactinemia but only in 4% of the general population." (PMID 37511458, 2023). "During COS serum prolactin levels increased significantly from baseline values leading to transient hyperprolactinemia." (PMID 36678618, 2023). "Across all measurements, prolactin abnormalities were most frequent (25.4%), with hypoprolactinemia constituting 14.1%, and hyperprolactinemia constituting 11.3%, followed by high FSH (13.1%), high LH (12.5%), and high ACTH (9.8%)." (PMID 37886645, 2023). "Prolactin measurement at the baseline visit found asymptomatic hyperprolactinemia in 21.8% of patients in the cohort overall." (PMID 37697708, 2023). "Risperidone, amisulpride, and first-generation antipsychotics (FGAs) such as thioridazine, thiothixene, and haloperidol have been reported to have a high prevalence of hyperprolactinemia and an overall prolonged rise in prolactin levels." (PMID 38143631, 2023). "A review of the effects of antipsychotics on prolactin levels and menstruation in women concluded that regular menses play an important role in reproductive and physical health, while hyperprolactinemia interferes with both menstrual regularity and fertility." (PMID 37759839, 2023). "Prolactin-producing pituitary adenoma, or prolactinoma, is in almost all cases a benign pituitary tumor that expresses and secretes prolactin, leading to hyperprolactinemia." (PMID 36835974, 2023). "In turn, metformin-induced reduction in prolactin levels in men was observed only if hyperprolactinemia was accompanied by low testosterone levels, and this effect inversely correlated with testosterone and calculated free testosterone levels." (PMID 37685540, 2023). "Hyperprolactinemia (elevated PRL levels) is a natural and beneficial phenomenon during pregnancy and lactation." (PMID 36833950, 2023). "Serial sampling was performed by drawing venous blood at different time intervals (0, 30 and 60 min) by single venipuncture to measure serum prolactin to diagnose stress-induced hyperprolactinemia." (PMID 36596817, 2023). "In clinical practice, the term hyperprolactinemia is typically used when PRL levels chronically increase." (PMID 36833950, 2023). "In this study, we found that the level of PRL also increased significantly in the observation group, and hyperprolactinemia was common in pituitary dysfunction or space-occupying lesions in the pituitary." (PMID 36743954, 2023). "Neuroleptics have a D2R blocking effect and can therefore increase the secretion of PRL, and drug-induced hyperprolactinemia after antipsychotic treatment is well-documented." (PMID 36833950, 2023). "The decrease in total and monomeric prolactin levels was observed in all 28 patients belonging to group 2, independently of the reason for hyperprolactinemia." (PMID 37297964, 2023). "Prolactin level of 59.2-120.55 ng/ml, as well as basal prolactin of 63.75 ng/ml and peak/baseline prolactin <1.5 detected by the metoclopramide test were suggestive of hyperprolactinemia." (PMID 37795364, 2023). "They found similar fertilization and cleavage rates in patients classified as having hyperprolactinemia (prolactin ≥ 30 μg/L) and those with normal prolactin levels." (PMID 36678618, 2023). "Nonetheless, one large study including 529 patients with acromegaly described a higher rate of females among patients with acromegaly and hyperprolactinemia than among those acromegalic patients with normal PRL levels (64.7 vs. 50%, p = 0.001)." (PMID 37762304, 2023). "Lactotroph PitNETs, which express and/or secrete prolactin (PRL), can cause various symptoms, such as hyperprolactinemia, galactorrhea, amenorrhea, infertility, headache, and visual defects." (PMID 37250410, 2023). "Knowingly, antipsychotics block D2 receptors and thus increase prolactin secretion, resulting in hyperprolactinemia." (PMID 37875841, 2023).
hyperprolactinemia (continued). "PRL is secreted by the anterior pituitary gland, and studies have shown that women with hyperprolactinemia and prolactinomas have a higher incidence of vertebral fractures when compared to the normal population." (PMID 37182163, 2023). "Despite the existence of evidence in terms of the association between PRL and PCOS, it is suggested that in cases of co-existence of PCOS and hyperprolactinemia, investigation of the classical etiologies of PRL abnormality is necessary." (PMID 36552931, 2022). "Hypothyroidism leads to a compensatory increase in the production of thyrotropin-releasing hormone (TRH) by the hypothalamus, which in turn results in suppression of dopamine production, resulting in excessive prolactin secretion, i.e. hyperprolactinemia." (PMID 36733805, 2022). "The mechanism by which neuroleptic drugs induce hyperprolactinemia involves regulation of dopamine and PRL in the brain." (PMID 35339194, 2022). "Typical antipsychotics were reported to have higher occurrences of elevated serum prolactin levels (hyperprolactinaemia) in comparison with atypical antipsychotic users." (PMID 36059215, 2022). "It has been reported that bromocriptine is effective in the treatment of hyperprolactinemia with prolactinoma, as bromocriptine effectively regulates prolactin, reestablishes gonadal function, and reduces tumor volume." (PMID 35356252, 2022). "In a series of 78 women affected by PRL-secreting pituitary adenomas, the prevalence of vertebral fracture appeared to be related to the length and severity of hyperprolactinemia, to BMD T-score value, and to the treatment." (PMID 35000899, 2022). "Common choices for the management of hyperprolactinaemia include switching the patient to a prolactin-sparing antipsychotic or additional use of D2 receptor agonist such as bromocriptine or cabergoline, however with increasing risk of adverse effects." (PMID 35992380, 2022). "Current data indicate that both conventional antipsychotics and high doses of risperidone (>6 mg/day) increase prolactin levels to the apparent clinical symptoms of hyperprolactinemia." (PMID 35207735, 2022). "Adjunctive aripiprazole or switching to aripiprazole in titration has been proved to be good PRL decrease effects (more than 50 ng/mL) for antipsychotic-induced hyperprolactinemia." (PMID 36313772, 2022). "Two of these patients have returned to cabergoline therapy despite ongoing side effects, with one achieving a normal serum prolactin level, while two patients have elected to remain off all treatment with ongoing hyperprolactinemia." (PMID 35608811, 2022). "This again highlights the importance of avoiding prolactin-raising antipsychotics in women to prevent hyperprolactinaemia." (PMID 34763737, 2022). "In recent years, it has been found that elevated levels of monomeric prolactin (hyperprolactinemia) and excess of high molecular weight prolactin (macroprolactinemia) attenuate the pleiotropic effects of atorvastatin." (PMID 36195057, 2022). "DA normalizes serum PRL levels in almost 90% of patients with idiopathic hyperprolactinemia or microP and in 75–80% of patients with macroadenomas." (PMID 35000899, 2022). "In cases of severe hyperprolactinemia (>200 ng/mL), the presence of a prolactinoma should be considered, although it can present with any level of PRL elevation." (PMID 35892862, 2022). "Recently, we demonstrated that juvenile hyperprolactinemia alters OB mitral cell activation in female mice exposed to social odors, suggesting that PRL participates in the maturation and response of the OB circuits." (PMID 35173591, 2022). "A pituitary hormone panel found isolated hyperprolactinemia (prolactin 1898 mIU/L, normal range 50-500 mIU/L), from which she was symptomatic with oligomenorrhea." (PMID 35323929, 2022). "A young woman was found to have hyperprolactinemia (serum prolactin 470 ng/ml) while being investigated for secondary amenorrhea." (PMID 35608811, 2022).
hyperprolactinemia (continued). "The monomeric or little PRL represents 80–95% of the total PRL in cases with normoprolactinemia and true hyperprolactinemia." (PMID 35000899, 2022). "One is that the induction of acute hyperprolactinemia by PRL injection leads to a decrease in pituitary proliferation and an increase in the apoptotic rate, particularly in lactotroph cells." (PMID 36714572, 2022). "Currently, dopamine agonists (DAs) are highly effective in achieving the goals to normalize prolactin and ameliorate the symptoms of hyperprolactinemia." (PMID 35807204, 2022). "Hyperprolactinemic mice overexpressing PRL in the liver have enhanced levels of circulating vasoinhibin, and pharmacologically induced hyperprolactinemia results in higher levels of vasoinhibin in ocular tissues and fluids of rats and humans." (PMID 35721729, 2022). "Hyperprolactinemia promotes the conversion of PRL to vasoinhibin, a PRL fragment that directly stimulates and indirectly inhibits (via an antiangiogenic mechanism) joint inflammation in a context- and cell type-dependent manner." (PMID 35721729, 2022). "The etiology of hyperprolactinemia was probably the reduction of dopamine from the hypothalamus, which is the dominant negative hypothalamic regulation on PRL secretion." (PMID 35360427, 2022). "In our study, the intensity of hyperprolactinemia was more expressed in the HD group (median PRL serum concentration 21.7 ng/mL) than in the PreD group (median PRL serum concentration 10.1 ng/mL p < 0.0001)." (PMID 36014950, 2022). "A recent study addressing the consequences of elevated PRL in CKD proposed that the diagnosis of hyperprolactinemia in this population is difficult and dialysis therapies, such as conventional hemodialysis and peritoneal dialysis, do not normalize PRL levels." (PMID 35173591, 2022). "Nowadays, the guidelines for the treatment of hyperprolactinemia mainly recommend CAB as the treatment of choice to control circulating PRL levels and eventual lactotroph tumour growth, in case of PRL-secreting pituitary tumours." (PMID 35460460, 2022). "A young woman with secondary amenorrhea was found to have mild hyperprolactinemia (serum prolactin 48 ng/ml)." (PMID 35608811, 2022). "Patients with GH(+)PRL(+) tumors presented hyperprolactinemia more frequently than patients with GH(+) and plurihormonal tumors, but the difference was not significant (41.7% vs. 26.9%, p=0.148)." (PMID 36187106, 2022). "Excessive PRL secretion leads to hypogonadism in both sexes, with the type and severity of clinical symptoms depending on the sex, PRL levels, disease duration, tumor size, and the extent of hyperprolactinemia." (PMID 36558529, 2022). "Hyperprolactinemia is unlikely a symptom of psychiatric disorders as the level of prolactin found in healthy adults and patients with psychiatric conditions prior to drug administration are comparable." (PMID 36619589, 2022). "Regarding possible mechanisms for the association between hyperprolactinemia and CVD risk, they include a possible direct effect of PRL, hypogonadism, and even effects of DA treatment, independently of changes in PRL levels." (PMID 36704037, 2022). "Elevated prolactin secretion and hyperprolactinaemia induced by prolonged dopamine receptor occupation have also been associated with increasing prevalence of obesity." (PMID 37861864, 2022). "Increased concentrations of PRL have rarely been reported in the so-called ‘neurogenic’ hyperprolactinemias, such as breast manipulation (mammoplasty, piercing), chest wall disease (as Herpes Zoster), or neurinoma of intercostal nerves." (PMID 35000899, 2022). "Benign breast tumour is another common side effect of 5-HT GPCR-targeted drugs predominantly seen in women since prolactin promotes breast cell division and prolonged hyperprolactinemia increases the risks of breast cancer." (PMID 36619589, 2022). "Hyperprolactinemia is defined as an increase in the level of the hormone prolactin to a level higher than normal in the blood." (PMID 35223307, 2022).